JARID2 (jumonji and AT-rich interaction domain containing 2)
Diseases named in the same sentence as JARID2 in open-access papers (continued):
Sharing a sentence is not in itself a finding about the gene and the disease.
bladder cancer (5 papers, 2010 to 2024). "In summary, our data indicated that Jarid2 expression was positively associated with bladder cancer cell invasion and sphere-forming ability in vitro." (PMID 28445934, 2017). "Knockdown of JARID2 has been reported to impair the invasive and tumorigenic abilities of bladder cancer cells, reducing the number of tumor-initiating cells, suggesting an important role of JARID2 in the progression of OSCC." (PMID 38961353, 2024). "Silencing of Jarid2 also decreased the percentage of TICs and inhibited the tumorigenicity of bladder cancer TICs." (PMID 28445934, 2017). "Collectively, we provided evidence that Jarid2 via modulation of p16 is a putative novel therapeutic target for treating malignant bladder cancer." (PMID 28445934, 2017). "Collectively, the data indicate that Jarid2 is an essential regulator in bladder cancer cells and can be used as a novel therapeutic target in the treatment of the disease." (PMID 28445934, 2017). "We found that knockdown of Jarid2 was able to inhibit the invasive ability and sphere-forming capacity in bladder cancer cells." (PMID 28445934, 2017). "Functionally, we found Jarid2 is required for the invasive ability and sphere-forming capacity in bladder cancer cells." (PMID 28445934, 2017). "In contrast, we only detected 2.4% and 5.8% ALDHhigh cells in Jarid2-sh 5637 and SCaBER cells, respectively, suggesting that the Jarid2 is necessary for ALDH activity in bladder cancer cells in vitro." (PMID 28445934, 2017). "We have characterized the role of Jarid2 over cell invasion, sphere-forming ability of bladder cancer and tumorigenicity of TICs." (PMID 28445934, 2017). "Conversely, ectopic overexpression of Jarid2 promoted the invasive ability and sphere-forming capacity in bladder cancer cells." (PMID 28445934, 2017). "Complementarily, forced expression of Jarid2 promoted the invasive ability and sphere-forming capacity in bladder cancer cells." (PMID 28445934, 2017). "In addition, Jarid2 expression was increased in bladder cancer tissues and cells, and upregulation of Jarid2 increased the H3K27me3 level at the PTEN promoter, thus enhancing the progression of bladder cancer through regulating PTEN/AKT signaling." (PMID 36292604, 2022). "To examine whether Jarid2 is critical for the tumorigenicity of bladder cancer TICs in vivo, we performed limiting dilutions (100, 500, 2500, 1 × 104 and 1 × 105) of ALDHhigh cell sorted from stable Jarid2-sh 5637 and SCaBER cells." (PMID 28445934, 2017). "Together, our results suggest that Jarid2 might play a role in the regulation of TICs in bladder cancer." (PMID 28445934, 2017). "In this study, we found that Jarid2 was enriched in the TICs of two bladder cancer cell lines." (PMID 28445934, 2017). "Interestingly, our results showed the level of p16INK4a transcript and protein was up-regulated in both Jarid2-sh bladder cancer cell lines." (PMID 28445934, 2017). "Moreover, knockdown of Jarid2 reduced the proportion of TICs and impaired the tumorigenicity of bladder cancer TICs in vivo." (PMID 28445934, 2017). "The goal of our study was to examine whether Jarid2 plays a role in the regulation of TICs in bladder cancer." (PMID 28445934, 2017). "However, the roles of Jarid2 in bladder cancer cells have remained elusive." (PMID 28445934, 2017). "To examine the function of Jarid2 in the ALDH activity and tumorigenicity of bladder cancer cells, we obtained stable bladder cell lines with lentivirus-mediated shRNA knockdown of Jarid2 compared with control cells expressing shGFP." (PMID 28445934, 2017).
Cognitive impairment (4 papers, 2013 to 2024). Abnormal cognition is characterized by deficits in thinking, reasoning, or remembering. "Moreover, deletions of JARID2 are associated with cognitive impairment and facial features such as prominent supraorbital ridges, deep set eyes, dark infraorbital circles, and midface hypoplasia." (PMID 25922617, 2015). "Patients carrying JARID2 deletion manifested with cognitive impairment, gait disturbance and a characteristic facial appearance, whereas patients with deletion of ATXN1 seemed to be characterized by intellectual disability and behavioural abnormalities." (PMID 23294540, 2013).
hepatocellular carcinoma (4 papers, 2016 to 2024). A malignant tumor that arises from hepatocytes. "In hepatocellular carcinoma, MiR-22 directly binds to JARID2 and plays an important role in MiR-22-mediated Th17 differentiation regulation." (PMID 38961353, 2024). "Moreover, JARID2 can regulate cell migration, invasion, proliferation and metastasis of hepatocellular carcinoma by repressing expression of tumor suppressor gene PTEN via increasing H3K27me3 level at PTEN promoter region." (PMID 28445934, 2017). "In addition, JARID2 positively mediates EMT of hepatocellular carcinoma via PTEN/AKT signaling, indicating a role of Jarid2 in the metastatic property of cancer cells." (PMID 28445934, 2017). "However, little is known about the role of JARID2 in metastasis of hepatocellular carcinoma (HCC)." (PMID 27259236, 2016). "For example, JARID2 is overexpressed in hepatocellular carcinoma (HCC) tissues, where its upregulation promotes EMT by inhibiting the phosphatase and tension homolog (PTEN)-induced AKT hyperactivation, resulting in enhanced invasion of HCC cells." (PMID 38961353, 2024).
cardiac hypertrophy (3 papers, 2019 to 2024). "MiR-155-deficient mice exhibited dampened cardiac hypertrophy upon TAC-induced pressure overload, most likely by relieving miR-155-induced inhibition of histone demethylase jumonji, AT rich interactive domain 2 (Jarid2)." (PMID 32252821, 2020). "Indeed, miR-155-dependent cardiac hypertrophy was found to be mediated by inhibiting the expression of jumonji AT-rich interactive domain 2 (Jarid2), a key transcriptional regulator of cardiac development and function with histone demethylase activity." (PMID 31547607, 2019). "The intersection of these databases yielded genes known to be involved in cardiac hypertrophy, including EZH2, NFATc4, GATA4, and JARID2." (PMID 38810124, 2024).
glioma (3 papers, 2022 to 2024). A benign or malignant brain and spinal cord tumor that arises from glial cells (astrocytes, oligodendrocytes, ependymal cells). "Overexpression of miR-155 in glioma cells leads to decreased JARID2 levels, promoting cell proliferation and survival." (PMID 39512697, 2024). "VPA, a histone deacetylase inhibitor, has been shown to modulate the miR-155/JARID2 axis, inducing apoptosis in glioma cells." (PMID 39512697, 2024). "During the development of glioma cells, the decrease of JARID2 leads to a reduction in phosphorylation levels of protein kinase B (Akt) and phosphatidylinositol-3-kinase (PI3K), which inhibits the proliferation, migration, and invasion of glioma cells." (PMID 38203196, 2023).
Insulin resistance (3 papers, 2022 to 2023). Increased resistance towards insulin, that is, diminished effectiveness of insulin in reducing blood glucose levels. "Vitamin D-deficient monocytes from human cord blood have comparable Jarid2/Mef2/PGC1a expression changes and secrete miR-106b-5p, causing adipocyte insulin resistance." (PMID 37311757, 2023). "Maternal indicators of insulin resistance and β-cell function in early pregnancy were associated with lower methylation at the CpG site cg03158092 located near the SYN3 gene and the CpG site cg05985988 located near the JARID2 gene, respectively." (PMID 36137169, 2022).
liver cancer (3 papers, 2022 to 2025). An epithelial or non-epithelial malignant neoplasm that arises from the liver. "The tumor cholangiocyte-like hepatocytes expressed KRT19 at higher levels than hepatocytes, as well as JARID2, which has been shown to be upregulated in liver cancers." (PMID 40766612, 2025). "In summary, we proposed a model in which EZH2 and JARID2 shift their RNA and DNA binding profiles between liver cancer and normal cell lines." (PMID 36578923, 2022). "Our study provided a comprehensive and distinct binding profile on RNAs and DNAs of EZH2 and JARID2 in liver cancer cell lines, suggesting their potential novel functional manners to promote HCC development." (PMID 36578923, 2022). "Stronger RNA binding ability and weaker DNA binding signal in tumor cells suggest that the canonical methyltransferase functions of EZH2 may be repressed in liver cancer cells, implying their novel regulatory mechanisms of EZH2 and JARID2 in promoting HCC occurrence and development." (PMID 36578923, 2022).
autism spectrum disorder (2 papers, 2012 to 2013). A spectrum of developmental disorders that includes autism, and Asperger syndrome. "We found that JARID2 and CD99 in our subnetwork and previous study have shown JARID2 functions together with CD99 in controlling autism spectrum disorder." (PMID 24328032, 2013).
Cirrhosis (2 papers, 2016 to 2022). A chronic disorder of the liver in which liver tissue becomes scarred and is partially replaced by regenerative nodules and fibrotic tissue resulting in loss of liver function. "We also did not detect correlations between high JARID2 expression in HCC tissues and gender, age, HBV infection, AFP, presence of cirrhosis, size of the tumor and presence of encapsulation." (PMID 27259236, 2016). "However, high JARID2 expression in HCC tissues did not correlate with gender, age, HBV infection, AFP, presence of cirrhosis, size of the tumor and presence of encapsulation." (PMID 27259236, 2016).
cleft palate (2 papers, 2019 to 2024). Cleft palate is a fissure type embryopathy that affects the soft and hard palate to varying degrees. "Additionally, JARID2 may serve as a downstream target gene in patients with cleft palate." (PMID 38961353, 2024). "The results suggest that the SNP rs4783099 in CRISPLD2 may contribute to an increased risk of NSCPO, and the SNP rs2237138 in JARID2 may hold a protective effect against non-syndromic cleft lip with or without cleft palate (NSCL ± P), in the Brazilian population." (PMID 31221977, 2019).
endometriosis (2 papers, 2021). The growth of functional endometrial tissue in anatomic sites outside the uterine body. "Despite the global downregulation seen in the micronome of endometriotic tissues, miRNAs that targeted JARID2 were highly expressed in the eutopic tissues of endometriosis patients who also experienced pain as a symptom." (PMID 33800594, 2021). "When compared to the EuN tissues, expression of all three PRC2 protein complex (SUZ12, EED and EZH2) and JARID2, was higher in both the eutopic (EuE) and ectopic (EcE) tissue from endometriosis patients." (PMID 33800594, 2021). "For example, iron oxidation, which occurs due to increased reactive oxygen species generation and known to be present in excess in women with endometriosis, blocks the catalytic activity of JARID2." (PMID 33800594, 2021). "This suggests that EZH2 in endo PF treated cells is having more of an effect on the expression of all genes in the array (PRC2 complex core, alternate and binding partners) when compared to JARID2 further supporting a role for EZH2 in endometriosis." (PMID 33800594, 2021). "Putting these results together with miR-155 transfection studies, this study suggests that while miR-155 and PHF19 may be the main helper in regulating the PRC2 complex in endometriosis, JARID2 may be taking up the slack when miR-155 is inhibited." (PMID 33800594, 2021). "Additionally, the role for PHF19 as the master-regulator of the miR-155-PRC2 complex-JARID2 crosstalk is also a viable candidate for therapy and should be further explored in endometriosis." (PMID 33800594, 2021). "Thus, targeting this demethylase (JARID2) via modulators such as microRNAs, could be a novel method of treatment for endometriosis." (PMID 33800594, 2021). "This study explored the role of miR-155 in endometriosis by studying its interactions with the PRC2 complex, JARID2 and FOXP3." (PMID 33800594, 2021). "ChIP-qPCR was used to better understand the regulatory roles of JARID2 and EZH2 and their cross-interactions in endometriosis." (PMID 33800594, 2021). "Here, using eutopic and ectopic tissues, as well as peritoneal fluid (PF) from IRB-approved and consented patients with and without endometriosis, the expression of PRC2 complex components, JARID2, miR-155 (known regulators of EZH2), and a key inflammatory modulator, FOXP3, was measured." (PMID 33800594, 2021).
glioblastoma (2 papers, 2023 to 2025). The most malignant astrocytic tumor (WHO grade IV). "In this study, we elucidated the role of NAT10 in enhancing glioblastoma (GBM) stemness by promoting JARID2 expression." (PMID 40288646, 2025).
Hyperglycemia (2 papers, 2023). An increased concentration of glucose in the blood. "The reduction of NO induced by hyperglycemia leads to an upregulation of Jarid2, an epigenetic repressor of Notch1." (PMID 37571325, 2023).
Impaired glucose tolerance (2 papers, 2023 to 2024). An abnormal resistance to glucose, i.e., a reduction in the ability to maintain glucose levels in the blood stream within normal limits following oral or intravenous administration of glucose. "Additionally, KO models of JARID2, TRIO, and ULK3 exhibited homeostasis and metabolism phenotypes, including increased circulating creatine, decreased circulating magnesium, impaired glucose tolerance, and increased circulating cholesterol." (PMID 39526184, 2024).
latent infection (2 papers, 2012 to 2024). "CMV latent infection associated hyper-methylated CpG sites are enriched in PcG proteins including RNF2, EZH2, KDM2B and JARID2." (PMID 39360678, 2024).
ovarian carcinoma (2 papers, 2022 to 2023). A malignant neoplasm originating from the surface ovarian epithelium. "JARID2 was also reported to be highly expressed in human ovarian cancer cell lines, and downregulation of JARID2 could significantly inhibit the cell proliferation, migration, invasion and epithelial-mesenchymal transition." (PMID 36471281, 2022).
psychosis (2 papers, 2018 to 2023). "In addition, a relationship between rs2235258 and rs9654600 on the JARID2 gene and the SCZ patients implied that JARID2 is an important psychosis gene in the population of the Changle area of Shandong Peninsula." (PMID 38203196, 2023). "Specifically, our results indicate that MEG3, a lncRNA that binds to a protein domain within JARID2 of the PRC2 repressome complex, is elevated in a subgroup of participants with psychosis." (PMID 30567388, 2018).
Viral infections (2 papers, 2019 to 2024). "Viral infections alter the expression of lysine demethylase 2B (KDM2B/NDY1), enhancer of zeste 2 polycomb repressive complex 2 subunit (EZH2) and JARID2." (PMID 39420919, 2024).
BAFopathy (1 paper, 2023). Disorder caused by mutations in the various subunits composing the BAF complex. "Notably, JARID2 exhibited the highest overlap with CHARGE (~7%, CHD7), BAFopathy (~4%, including ARID1A, ARID1B, SMARCB1, SMARCA2, SMARCA4), and the PCR2 complex, which houses Cohen–Gibson syndrome (COGIS) and Weaver syndrome (WVS) (~4%, EED, EZH2)." (PMID 37762546, 2023).
Bicuspid aortic valve (1 paper, 2016). The presence of an aortic valve with two instead of the normal three cusps (flaps). "Depletion of Brg1 in endothelial cells frequently results in bicuspid aortic valve in mice and endothelial JARID2 is required for normal cardiac development." (PMID 27760138, 2016).
cardiac tumors (1 paper, 2018). "The common JAGs responsible for heart diseases included: JARID2 and TBX20, associated with a structural heart anomaly; JAZF1, associated with cardiac tumors; CAMK2G, associated with conduction defects; and CMAK2D and TMPO, associated with dilated cardiomyopathy." (PMID 29449671, 2018).
CHARGE syndrome (1 paper, 2023). CHARGE syndrome is a multiple congenital anomaly syndrome characterized by the variable combination of multiple anomalies, mainly Coloboma; Choanal atresia/stenosis; Cranial nerve dysfunction; Characteristic ear anomalies (known as the major 4 C's). "CHARGE syndrome exhibited a ~7% overlap with the JARID2 cohort, and it is caused by variants in CHD7, characterized by multiple congenital anomalies." (PMID 37762546, 2023). "Notably, the HOXA5 DMR found in the JARID2-neurodevelopmental disorder is also hypomethylated in CHARGE syndrome, which may explain some of the clinical overlap observed between JARID2-neurodevleopmental disorder and CHARGE." (PMID 37762546, 2023).
Coffin–Siris syndrome-9 (1 paper, 2023). "A tree-and-leaf plot showed that the JARID2 genome-wide DNA methylation change is most closely related to the DNA methylation changes of Coffin–Siris syndrome-9 (CSS9; SOX11), myopathy, lactic acidosis, and sideroblastic anemia 2 (MLASA2; YARS2) and Lysine-demethylase 2B (KDM2B)." (PMID 37762546, 2023).
Cohen-Gibson syndrome (1 paper, 2023). "Furthermore, JARID2 DMPs also exhibited overlap with the PCR2 complex episignature that encompasses Cohen–Gibson syndrome (COGIS) and Weaver syndrome (WVS) DMPs." (PMID 37762546, 2023).
herpesvirus infection (1 paper, 2023). "The dysregulation of Jarid2 gene is observed during Kaposi sarcoma-associated herpesvirus infection and leads to cell transformation." (PMID 37700325, 2023).
lymph node metastasis (1 paper, 2024). "The results showed that the expression of JARID2 was related to age (p < 0.001), pathological grade (p = 0.441), T stage (p = 0.006), and lymph node metastasis factors (p = 0.029)." (PMID 38961353, 2024).
melanoma (1 paper, 2018). A malignant, usually aggressive tumor composed of atypical, neoplastic melanocytes. "The data showing that JARID2 and SFRP1 are inversely correlated in melanoma are intriguing and suggest that JARID2 and PRC2’s modulation of Wnt signaling is highly significant for many cellular systems." (PMID 30119689, 2018). "Finally, we show that JARID2 and SFRP1 are inversely correlated in melanoma, confirming that the JARID2-mediated repression of SFRP1 extends beyond skeletal muscle and has important implications in many cellular systems, including cancer." (PMID 30119689, 2018).
metastatic disease (1 paper, 2016). "This indicates that we may identify the subgroup of HCC patients who are at high risk of developing metastatic disease in advance according to JARID2 expression in HCC tissues." (PMID 27259236, 2016).
muscular dystrophies (1 paper, 2022). "Three of these genes, ETS1, NR3C1 and JARID2, are common in all five muscular dystrophies with no previous association with any of the five muscular dystrophies based on bibliography." (PMID 35388741, 2022).
myelodysplastic syndrome (1 paper, 2023). A clonal hematopoietic disorder characterized by dysplasia and ineffective hematopoiesis in one or more of the hematopoietic cell lines. "Also, the mRNA expression of DLK1 that has been implicated in myelodysplastic syndrome and the Polycomb repressive complex 2 (PRC2) member JARID2 were potentially de-regulated by nearby putative enhancers." (PMID 37495775, 2023).
myelofibrosis (1 paper, 2017). A partial or complete replacement of the bone marrow stroma by fibrous tissue. "In the primary myelofibrosis (PMF) study, the authors revealed that overexpressed miR-155-5p regulates JARID2, and they suggested that regulated JARID2 may be related to MK hyperplasia in PMF." (PMID 28362846, 2017).
myelogenous leukaemia (1 paper, 2021). "Given the functional resemblance between PALI1 to JARID2 and their potential role as tumour suppressors in hematopoietic malignancies, we wished to determine if PALI1 has a negative effect on the proliferation of myelogenous leukaemia cells." (PMID 34321472, 2021).
Obesity (1 paper, 2013). Accumulation of substantial excess body fat. "Here we report a 6p deletion of about 1 Mb encompassing five genes (ATXN1, DTNBP1, JARID2, MYLIP and GMPR), identified in a patient with severe ID, hypotonia, brain anomalies, EEG abnormalities, macrosomia, obesity, and ASDs with associated hyperactivity and behavioral abnormalities." (PMID 23324214, 2013).